NPBWR2 (neuropeptides B and W receptor 2)
Description:
Interacts specifically with a number of opioid ligands. Receptor for neuropeptides B and W, which may be involved in neuroendocrine system regulation, food intake and the organization of other signals.
Synonyms: GPR8
Tractability: Small molecule: it belongs to a druggable protein family. Antibody: its Gene Ontology location is reachable by antibodies, with high confidence; UniProt places it where antibodies can reach, with medium confidence; UniProt predicts a signal peptide or a membrane-spanning region.
Target class: Peptide receptor (family A GPCR); Family A G protein-coupled receptor; Short peptide receptor (family A GPCR); Membrane receptor; Neuropeptide receptor
Gene: Protein-coding gene on chromosome 20 (64,103,802 to 64,107,565, reverse strand). Ensembl gene ENSG00000125522.
Subcellular location: Cell membrane
Pathways (Reactome):
Signal Transduction: G alpha (i) signalling events; Peptide ligand-binding receptors
Gene Ontology:
Molecular function: protein binding; G protein-coupled opioid receptor activity; G protein-coupled receptor activity; neuropeptide binding; neuropeptide receptor activity
Biological process: G protein-coupled receptor signaling pathway; neuropeptide signaling pathway; G protein-coupled opioid receptor signaling pathway
Cellular component: membrane; neuron projection; plasma membrane
Genetic constraint (gnomAD): Loss-of-function variants: 0 observed, 0.2 expected, observed/expected ratio (o/e) 0, 90% interval 0 to 1.88. That is too few expected variants to judge how well the gene tolerates losing a copy. Missense variants: 390 observed, 477.27 expected, observed/expected ratio (o/e) 0.82, 90% interval 0.75 to 0.89. Synonymous variants: 207 observed, 231.75 expected, observed/expected ratio (o/e) 0.89, 90% interval 0.8 to 1.
Homologues: Orthologues: chimpanzee NPBWR2 (99% identical), guinea pig NPBWR2 (79% identical), pig NPBWR2 (79% identical), macaque NPBWR2 (79% identical), tropical clawed frog npbwr1 (62% identical), zebrafish npbwr2a (62% identical), dog KISS1R (28% identical), Caenorhabditis elegans trhr-1 (22% identical), Drosophila melanogaster Rh7 (22% identical). Paralogues in human: NPBWR1 (60% identical), SSTR5 (40% identical), OPRD1 (38% identical), SSTR3 (38% identical), OPRM1 (36% identical), SSTR2 (36% identical), SSTR4 (36% identical), OPRK1 (36% identical), SSTR1 (36% identical), OPRL1 (35% identical), KISS1R (29% identical), CMKLR2 (26% identical), and 5 more.
Diseases named in the same sentence as NPBWR2 in open-access papers:
NPBWR2 is named in the same sentence as 9 diseases in open-access papers, as found by Europe PMC text mining. Sharing a sentence is not in itself a finding about the gene and the disease. The quoted sentences say what the papers report.
cancer (2 papers, 2024). A tumor composed of atypical neoplastic, often pleomorphic cells that invade other tissues. "Intriguingly, we found several axes, such as NPBWR2-NPW or CALCR-CALCB, associated with lower survival more significantly than considering interaction partners alone in multiple cancer types." (PMID 38723607, 2024).
NPBWR2 also shares sentences with these, for which no sentence is quoted: breast carcinoma (1 paper); hepatocellular carcinoma (1); leukemia (1); lung carcinoma (1); lymphoma (1); melanoma (1); multiple myeloma (1); tumour (1).